CTTN (cortactin)
Diseases named in the same sentence as CTTN in open-access papers (continued):
Sharing a sentence is not in itself a finding about the gene and the disease.
infection (23 papers, 2008 to 2025). The state of being infected such as from the introduction of a foreign agent such as serum, vaccine, antigenic substance or organism. "To investigate cortactin’s precise function during H. pylori infection in more detail, we here employed CRISPR/Cas9-mediated genome editing to generate stable and complete Cortactin-deficient AGS cell lines (AGSΔcttn) subjected to infection experiments." (PMID 34205064, 2021). "In addition, cortactin has also been associated with the infection of various bacterial and viral pathogens." (PMID 31940955, 2020). "Cortactin has been implicated in the infection process of several microbial pathogens." (PMID 22761768, 2012). "To determine whether C. burnetii causes cortactin phosphorylation during infection, we examined the phosphorylation status of Tyr421 after different infection periods." (PMID 22761768, 2012). "Contrasting to cortactin and similar to actin, vinculin expression remained unchanged at all time points and under all infection conditions." (PMID 41341493, 2025). "Consistent with actin, the subcellular localization of cortactin and vinculin was also affected by infection." (PMID 41341493, 2025). "Multiple other studies have found a distinct role for cortactin during infection by the gastric pathogen Helicobacter pylori." (PMID 38646547, 2024). "Western blot analyses revealed that infection with H. pylori wt induced the formation of a protein complex harboring CagA, Par1b, cortactin and ZO-1." (PMID 38646547, 2024). "Prior work indicated that TNFα induces cortactin redistribution in ECs to the site of PMN transmigration, with cortactin also involved in pronounced NF-κB activation and IL-8 release upon infection." (PMID 39162263, 2024). "We next aimed to study the localization of the cortactin/ZO-1 complex within cells upon infection with H. pylori." (PMID 38646547, 2024). "After infection, we immunostained the cells with α-cortactin, α-Par1b and α-FLAG antibodies as well as DAPI." (PMID 38646547, 2024). "Infections with H. pylori were recently shown to affect the phosphorylation status both of cortactin and Par1b via the injected effector protein CagA." (PMID 38646547, 2024). "Knockdown of the expression of CTTN promoted the infection of HeVpv significantly (p < 0.0001), and with the increase in CTTN expression, the infection of HeVpv was increasingly inhibited." (PMID 38612921, 2024). "In several past studies, CTTN has been found to be involved in the infection process of a variety of viruses." (PMID 38612921, 2024). "Since there is no BSL-4 laboratory in this experiment, only pseudoviruses can be used for infection experiments, which can only indicate that CTTN interacts with F and G and has the possibility of mediating the infection of NiV." (PMID 38612921, 2024). "In conclusion, this study constructs a robust protein database for global drug discovery teams to develop therapeutic drugs to defend against NiV and demonstrates that CTTN is a potentially relevant host factor for the infection of NiV." (PMID 38612921, 2024). "Then, NiVpv was seeded into siRNA-treated cells and detected by luciferase, and the results showed that knockdown of CTTN promoted the infection of NiVpv in HEK293T cells significantly (p < 0.0001)." (PMID 38612921, 2024). "In agreement, an interplay between the focal adhesion kinase, cortactin and Src kinase facilitates infection of N. meningitidis into human brain microvascular endothelial cells by inducing a cytoskeletal rearrangement and uptake of the pathogen." (PMID 37065199, 2023). "Endothelial cortactin is necessary for proper regulation of neutrophil transendothelial migration and recruitment to sites of infection." (PMID 35625756, 2022). "Influenza A virus (IAV) infection of epithelial cells results in degradation of CTTN, with CTTN undergoing ubiquitination during IAV infection in a lysosome-associated apoptotic pathway." (PMID 35562995, 2022).
infection (continued). "We have previously shown that H. pylori targets cortactin upon infection of gastric epithelial cells." (PMID 34439396, 2021). "As the next step, we aimed to study if the expression of cortactin and Vav2 were required for the activation of Rac1 during infection." (PMID 34439396, 2021). "Here, we investigate the role of tyrosine-phosphorylated cortactin during infection of AGS gastric epithelial cells." (PMID 34439396, 2021). "Cortactin has been also reported as a target of several other microbial pathogens, which change its phosphorylation status for various purposes upon infection." (PMID 34439396, 2021). "The results showed that wt H. pylori, but not ∆cagA mutant, induced the predominant phosphorylation of cortactin at Y-470 between 2 and 4 h of infection." (PMID 34439396, 2021). "Upon infection with H. pylori, cortactin not only undergoes CagA-mediated tyrosine dephosphorylation but also serine phosphorylation at S-405 and S-418 by PAK1 or ERK1/2 serine-threonine kinases." (PMID 31936446, 2020). "Before zooming in on the role of H. pylori in cortactin-dependent cell signaling, its virulence factors and their role in pathogenicity during infection are briefly summarized first." (PMID 31936446, 2020). "During infection, H. pylori targets, amongst others, the cellular protein cortactin that is crucial for correct regulation of cytoskeletal rearrangements in healthy cells." (PMID 31936446, 2020). "It has been proposed that H. pylori targets cortactin to protect the gastric epithelium from excessive cell lifting and ensure sustained infection in the stomach." (PMID 28338646, 2017). "Upon infection, serine-phosphorylated cortactin was found to interact with and stimulate the activity of focal adhesion kinase (FAK) which triggered enhanced cell adhesion and elongation." (PMID 28338646, 2017). "Cortactin has emerged as a key cellular protein that microbes readily subvert during the establishment of infection." (PMID 24188565, 2013). "Infection of cortactin-EGFP transfected cells with the C. jejuni wild-type strain resulted in distinct membrane ruffling." (PMID 24188565, 2013). "Analysing the phosphorylation pattern in FAK+/+ expressing cells, we demonstrated that infection with N. meningitidis also induced enhanced tyrosine phosphorylation of the actin-filament binding protein cortactin." (PMID 22768099, 2012). "We observed that Src kinase was activated at 15 min of infection and then the levels of activated enzyme decreased to basal levels, while cortactin was phosphorylated on Tyr421 at 1 h of infection." (PMID 22761768, 2012). "They showed that cortactin is phosphorylated upon infection with meningococci and that phosphorylation is crucial for efficient invasion." (PMID 22768099, 2012). "Despite the decrease in kinase activity, cortactin phosphorylation at Tyr421 reached a peak at 1 h of infection." (PMID 22761768, 2012). "Cortactin is a key regulator of the actin cytoskeleton which plays a crucial role in cell invasion and actin-based motility during the infection of many microbial pathogens." (PMID 19419567, 2009). "In our system, EPEC-infected cells still showed high levels of N-WASP-dependent cortactin phosphorylation three hours after infection." (PMID 19419567, 2009). "L2 infection of HeLa cells induced tyrosine phosphorylation of WAVE2, Vav2, and Cortactin at 1 hour post infection (lane 2)." (PMID 18369471, 2008). "The result also indicates that CTTN could inhibit the infection of NiVpv, which is consistent with the overexpression results." (PMID 38612921, 2024). "In addition, through further validation of PPIs, we found that CTTN interacts with both NiV F and NiV G and inhibits the infection of NiVpv into host cells." (PMID 38612921, 2024). "The infection titers of pseudovirus were detected by luciferase, and the results showed that the infection of NiVpv was inhibited with the increase in the expression of CTTN." (PMID 38612921, 2024).
infection (continued). "In addition, in RSV, it has been found that CTTN can inhibit its infection by protecting the epithelial barrier." (PMID 38612921, 2024). "However, studies regarding the impact of cortactin during infection with H. pylori have mostly relied on in vitro experiments using knockdown of cortactin e.g., by RNA interference." (PMID 34205064, 2021). "Hence, we believe that in the early stages of infection intact cortactin is required for IAV entry to maintain dynamic branched filamentous actin network for efficient endocytosis of incoming virions." (PMID 31940955, 2020). "Infection of INT 407 cells with a C. jejuni wild-type strain resulted in a significant increase (above uninfected cells) in the amount of phosphorylated (activated) cortactin." (PMID 24188565, 2013). "Thus, the results reported here indicate that dynamic phosphorylation of cortactin is important for C. burnetii internalization during infection." (PMID 22761768, 2012). "Interestingly, a study by Backert and co-workers recently discovered FAK as a binding partner of cortactin based on immunofluorescence and immunoprecipitation experiments using transfection and infection with Helicobacter pylori as a model organism." (PMID 22768099, 2012). "Moreover, we observed cortactin phosphorylation on Tyr421 at 1 h of infection with C. burnetii, after which the phosphorylation returned to basal levels." (PMID 22761768, 2012). "Interestingly, cortactin is recruited to the contact sites made by several pathogens with the host plasma membrane during infection." (PMID 22761768, 2012). "In addition, CTTN can also inhibit the infection of the Hendra pseudovirus (HeVpv) in 293T cells." (PMID 38612921, 2024). "However, higher numbers of neutrophils in the blood of septic CTTN KO mice could imply a better immune response to spreading infection at later stages thus contributing to better survival of septic CTTN KO mice." (PMID 35625756, 2022). "While the role of the tyrosine-dephosphorylated form during infection is not yet clear, cortactin phosphorylated at S-113 promoted the loss of F-actin binding; and cortactin phosphorylated at S-405 was required for binding and activation of focal adhesion kinase (FAK)." (PMID 34439396, 2021). "To explore the function of CTTN, SERBP1, and STMN1 in infection of NiV, we conducted pseudoviral infection experiments." (PMID 38612921, 2024). "The level of cortactin was also found to be downregulated in influenza A virus-infected MDCK and A549 cells 24 h after infection." (PMID 35848790, 2022). "In contrast, infection of AGS cells transfected with siRNAs, interfering with cortactin, Vav2 or Rac1 expression exhibited strongly reduced wound healing activities." (PMID 34439396, 2021). "Together, these results confirm that phosphorylation of cortactin at Y-470 positively regulates AGS cell motility and wound healing upon infection with H. pylori." (PMID 34439396, 2021). "During infection of AGS cells, cortactin was discovered to undergo tyrosine dephosphorylation at residues Y-421 and Y-486, which is mediated through inactivation of Src kinase." (PMID 34439396, 2021). "Together, we report here a yet unrecognized cortactin-dependent signaling pathway involving FAK, Src, and Abl activation, and controlling efficient phosphorylation of injected CagA during infection." (PMID 34205064, 2021). "In this study, infection with CagA+H. pylori led to a decrease in cortactin levels, but not vinculin, in BxPC-3 cells." (PMID 41341493, 2025). "Infection of the H9N2 AIV was indicated by virus NS1 protein, and the amount of five cell surface proteins relating to bacteria adhesion, including fibronectin, integrin α5, occludin, cortactin, and ZO-1, was measured by Western blot." (PMID 38415626, 2024). "Infection with H. pylori wt, but not with the ΔcagA mutant, was characterized by an even more pronounced redistribution of Par1b and cortactin from basal to apical sides." (PMID 38646547, 2024).
infection (continued). "By contrast, cortactin deficiency only reduces and does not ablate neutrophil recruitment, so that neutrophils in certain amounts are recruited even in the absence of cortactin, which can contribute to fighting the infection." (PMID 35625756, 2022). "INT 407 cells infected with the C. jejuni ciaD complemented isolate restored the phosphorylation of cortactin to levels indistinguishable from infection with a C. jejuni wild-type strain." (PMID 24188565, 2013). "Specifically, infection with the C. jejuni wild-type strain and the ciaD complemented isolate resulted in a significant increase in the level of activated cortactin, but the C. jejuni ciaD mutant was indistinguishable from uninfected cells." (PMID 24188565, 2013). "Internalization of Chlamydia trachomatis also involves cortactin, and this protein is phosphorylated at 1 h of infection by Abl kinases but not Src." (PMID 22761768, 2012). "Early after infection, Src and ERK kinases may phosphorylate unknown substrates, perhaps other kinases such as Abl that in turn phosphorylate tyrosine residues in cortactin." (PMID 22761768, 2012). "Cortactin tyrosine phosphorylation is dependent on the pathogen: it occurs upon infection with Shigella, Vaccinia virus and Cryptosporidium, whereas cortactin phosphorylation is not necessary for uptake of EPEC and EHEC." (PMID 22768099, 2012). "Reduction of cortactin expression by siRNA or over-expression of its isolated SH3 domain, polyproline region or its α-helical region resulted in a drastic decrease in actin-pedestal formation during infection with EPEC." (PMID 19419567, 2009). "We propose that H. pylori induces the phosphorylation of Y-470 in cortactin to locally open the gastric epithelium at sites of infection, perhaps to retrieve important nutrients likely absent in the gastric lumen, and thus, disturbing cellular barrier functions." (PMID 34439396, 2021). "In addition to that, we found that the 3F cortactin mutant with non-phosphorylatable tyrosines enhances C. burnetii entry at 4 h after infection." (PMID 22761768, 2012). "Using this approach, we discovered that cortactin is required for profound activation of the non-receptor tyrosine kinases FAK, Src, and Abl, followed by efficient phosphorylation of injected CagA upon infection." (PMID 34205064, 2021).
bacterial infection (3 papers, 2013 to 2022). "Equally important, it contributes to the understanding of the phosphorylation of cortactin in bacterial infection." (PMID 24188565, 2013).
head and neck tumors (3 papers, 2008 to 2024). "Over-expression of CTTN has been observed, which is a significant factor in the development of head and neck tumors, particularly in the progression of lymph node metastasis." (PMID 38225277, 2024).
adenocarcinoma (2 papers, 2014 to 2021). A common cancer characterized by the presence of malignant glandular cells. "In the third panel of 6 adenocarcinoma-derived cell lines, a preferential knockdown of CTTN was observed across the board, and even in the case of alternate targets, the resulting knockdowns were much more conserved." (PMID 24987961, 2014). "Finally, cortactin has been described as a potential biomarker in various adenocarcinoma and indicates a poor survival prognosis for patients." (PMID 34205064, 2021).
retinopathy (1 paper, 2015). "In light of past work from our laboratory on the role of Tbdn loss in endothelial hyperpermeability in retinopathy, the work herein provides evidence that Tbdn acts through the c-Src/Cortactin pathway to maintain homeostasis of retinal blood vessels." (PMID 26142315, 2015).
CTTN also shares sentences with these, for which no sentence is quoted: esophageal tumors (2 papers); Helicobacter infection (2); lung adenocarcinoma (2); nasopharyngeal carcinoma (2); thymoma (2); acute kidney injuries (1); acute lymphoblastic leukemia (1); Adrenocortical Carcinoma (1); carotid atherosclerosis (1); Colon (1); COVID-19 (1); dementia (1); differentiated thyroid carcinoma (1); emphysema (1); encephalitis (1); endometrioid adenocarcinoma (1); gliosarcoma (1); HIV-1 infection (1); hypertrophy (1); hypopharyngeal cancer (1); intrahepatic cholangiocarcinoma (1); Kufor-Rakeb syndrome (1); Lambert-Eaton myasthenic syndrome (1); liver diseases (1); mucinous carcinomas (1); myopathy (1); nephrotic syndrome (1); neurodegenerative disease (1); odontogenic keratocyst (1); Parkinsonism (1).
A further 4 diseases each share a sentence with CTTN in 1 paper.